ORAI1 (ORAI calcium release-activated calcium modulator 1)
Diseases named in the same sentence as ORAI1 in open-access papers (continued):
Sharing a sentence is not in itself a finding about the gene and the disease.
heart failure (11 papers, 2019 to 2025). Inability of the heart to pump blood at an adequate rate to meet tissue metabolic requirements. "Moreover, cardiac fibroblasts isolated from patients with heart failure possess an enhanced ability to synthesize collagen, which is linked to increases in store-operated Ca2+ entry and Orai1 expression." (PMID 36232526, 2022). "Orai3 deletion also results in dilated cardiomyopathy and heart failure in mice, while Orai1 suppression results in reduced cardiomyocyte fractional shortening and heart failure in zebrafish." (PMID 39574715, 2024). "Studies in Zebrafish were amongst the first to indicate a significant role of Orai1 in the heart, where Orai1 deletion resulted in the development of heart failure and significant ultrastructural defects." (PMID 35821821, 2022). "We examined the role of ORAI1/SOCE as a new mechanism for the prevention of DOX-induced heart failure." (PMID 36472998, 2022). "In this study, we examined the relationship between DOX-induced heart failure and ORAI1/SOCE in CFs, which, to our knowledge, is unprecedented." (PMID 36472998, 2022). "Ventricular fibroblasts derived from patients with heart failure exhibited increased Orai1, but similar STIM1 protein expression levels compared to those of non-failing hearts." (PMID 35008591, 2021). "Heterozygous Orai1+/− mice of a C57BL6/J genetic background with ~25% reduction of Orai1 protein expression in the heart exhibit faster development of heart failure after TAC." (PMID 32354146, 2020). "Previous studies have demonstrated that cardiomyocyte-specific STIM1 suppression in mice results in age-dependent cardiomyopathy and heart failure in adults, whereas severe heart failure was evident during embryogenesis in zebrafish with Orai1 suppression." (PMID 32086252, 2020). "Additionally, Orai1 suppression in zebrafish embryos resulted in reduced fractional shortening and severe heart failure." (PMID 32086252, 2020). "ORAI1 may be a new target for preventing DOX-induced heart failure." (PMID 36472998, 2022). "ORAI1 may serve as a new target for preventing DOX-induced heart failure." (PMID 36472998, 2022). "In a recent study, we provided proof of concept that the Orai1 Ca2+ channel should be considered as an innovative therapeutic candidate for PAH and heart failure." (PMID 41212057, 2025). "A recent study demonstrated that ORAI1, and thus SOCE, was upregulated in cardiac fibroblasts from failing ventricles, indicating the pivotal role played by CF ORAI1 in heart failure." (PMID 36472998, 2022). "However, whether ORAI1 is related to the progression of DOX-induced heart failure remains unknown." (PMID 36472998, 2022). "In this study, we aimed to elucidate the relationship between ORAI1/SOCE and DOX-induced heart failure." (PMID 36472998, 2022). "We demonstrate that ORAI1/SOCE may be a potential new target for the prevention and treatment of DOX-induced heart failure." (PMID 36472998, 2022). "The reduction in Orai1 levels was restricted to male patients, suggesting that sex differences could exist in the expression of STIM-Orai family members, which have not been examined in detail and could contribute to documented sex differences that exist in heart failure progression." (PMID 35821821, 2022).
cervical cancer (10 papers, 2012 to 2023). A primary or metastatic malignant neoplasm involving the cervix. "These clinical data suggested a strong association between Orai1 expression and cervical cancer progression." (PMID 36310590, 2022). "They concluded that Orai1 was strongly associated with cervical cancer progression." (PMID 37759164, 2023). "Furthermore, the exact biological functions of Orai1 in cervical cancer and the underlying mechanisms are still poorly understood." (PMID 36310590, 2022). "Real-time quantitative polymerase chain reaction (RT-qPCR) showed that mRNA transcription of Orai1 was approximately fivefold higher in 62% (13/21) of the cervical cancer tissues compared to the normal tissues." (PMID 37759164, 2023). "This is the first study to explore the biological function and molecular mechanism of Orai1 in cervical cancer." (PMID 36310590, 2022). "Taken together, our findings indicate that Orai1 functions as an oncogene in cervical cancer and is a promising therapeutic target." (PMID 36310590, 2022). "To further determine the biological role of Orai1 in cervical cancer, we knocked down the Orai1 transcript in Caski and SiHa cells using two specific siRNAs, and both suppressed Orai1 mRNA and protein expression." (PMID 36310590, 2022). "Analysis of the RNA-seq data of cervical cancer patients from The Cancer Genome Atlas (TCGA) revealed that Orai1 mRNA levels were significantly higher in the tumor tissues compared to the normal cervical tissues." (PMID 36310590, 2022). "To further validate role of IL-6 in Orai1-mediated cell growth, we treated the Orai1-silenced cervical cancer cells with recombinant IL-6." (PMID 36310590, 2022). "In this study, we found that Orai1 was upregulated in cervical cancer tissues, and promoted the growth of human cervical cancer cells both in vitro and in vivo." (PMID 36310590, 2022). "Gene silencing of Orai1 in cervical cancer cells significantly decreased interleukin (IL)-6 secretion." (PMID 36310590, 2022). "In conclusion, we highlighted the functional role of Orai1-mediated SOCE in cervical cancer, which warrants further assessment as a therapeutic target." (PMID 36310590, 2022). "In this study, we found that Orai1 is upregulated in cervical cancer tissues compared to normal cervical tissues, and its high expression levels correlated positively with that of IL-6." (PMID 36310590, 2022). "We found that Orai1 was upregulated in human cervical cancer tissues, and silencing Orai1 suppressed the growth of cervical cancer cells in vitro and in vivo via inhibition of IL-6 secretion." (PMID 36310590, 2022). "In this study, we found that genetic knockdown and pharmacological inhibition of Orai1 reduced SOCE in cervical cancer cells, which in turn inhibited their growth in vitro and in vivo." (PMID 36310590, 2022). "Consistent with this, pre-treatment with IL-6 enhanced the clonogenicity of Orai1-knockdown cervical cancer cells, indicating that IL-6 lies downstream of Orai1." (PMID 36310590, 2022). "Taken together, inhibiting Orai1 expression suppressed the proliferative capacity of cervical cancer cells in vitro and in vivo, indicating that Orai1 is essential for cervical cancer progression." (PMID 36310590, 2022). "Given the importance of SOCE tumor biology and cancer progression, it is plausible to suggest that the blockade of STIM1/Orai1-dependent Ca2+ signaling can be a practical therapeutic approach for cervical cancer." (PMID 35008759, 2021). "The functional significance of STIM1/Orai1-dependent SOCE in tumor angiogenesis was confirmed by a study using the model of SiHa cervical cancer cells." (PMID 31252656, 2019). "Dysregulated expression of ORAI1 and STIM1 genes was found in several types of cancer and has been linked to more aggressive forms of breast and cervical cancer." (PMID 23922331, 2013). "Furthermore, they also demonstrated a positive correlation between Orai1 and IL-6 expression in human cervical cancer samples." (PMID 37759164, 2023).
cervical cancer (continued). "Silencing of Orai1 by siRNA attenuated SOCE in human cervical cancer cells (Caski or SiHa cells)." (PMID 37759164, 2023). "Furthermore, they evaluated 87 patient cervical cancer tissue samples and 34 normal cervical tissues by IHC staining, and the results showed that Orai1 protein expression was significantly higher in the tumor samples." (PMID 37759164, 2023). "Interestingly, exogenous IL-6 abrogated the effects of Orai1 silencing and restored the clonogenicity of cervical cancer cells." (PMID 36310590, 2022). "Taken together, Orai1 mediates TG-induced SOCE in cervical cancer cells." (PMID 36310590, 2022). "Finally, Orai1 knockdown also repressed IL-6 secretion from the cancer cells, indicating that the oncogenic effects of Orai1 in cervical cancer is mediated via increased production of IL-6." (PMID 36310590, 2022). "Furthermore, immunohistochemical assessment of 87 cervical cancer tissues and 34 normal cervical tissues indicated that Orai1 protein expression was significantly higher in the tumor samples." (PMID 36310590, 2022). "Furthermore, we also observed a positive correlation between Orai1 and IL-6 expression in human cervical cancer samples." (PMID 36310590, 2022). "Taken together, inhibition of Orai1 decreased IL-6 expression in cervical cancer cells." (PMID 36310590, 2022). "Taken together, Orai1 promotes the growth of cervical cancer cells by increasing IL-6 expression." (PMID 36310590, 2022). "Since Ca2+ is essential for cell growth, we next investigated whether Orai1 also affects the growth of cervical cancer cells." (PMID 36310590, 2022). "Furthermore, Orai1 expression was positively correlated with IL-6 expression in the cervical cancer tissues." (PMID 36310590, 2022). "Pharmacological or siRNA inhibition of the STIM1/Orai1 pathway of SOCE activation in human cervical cancer cells resulted in the decreased phosphorylation of CDK2 and the excursive expression of cyclin E, leading to autophagy accompanied with a cell cycle arrest in G1/S transition." (PMID 31252656, 2019). "In cervical cancer, a recent study found that histone deacetylase 6 (HDAC6) is required for STIM1 translocation on microtubules and thus activates Orai1-mediated SOCE." (PMID 36230965, 2022). "Aberrated overexpression of STIM1 or Orai1 and thus upregulated SOCE activity have been observed in several types of human cancers, including cervical cancers." (PMID 35008759, 2021). "Among the patients suffering from colorectal cancer, gastric cancer, cervical cancer, a correlation between STIM1 and/or Orai1 expression levels and poor prognosis with fast metastatic progression has been detected." (PMID 33333945, 2020). "It is well documented that both STIM1 and Orai1 are required for function of SOCE and STIM1 was particularly reported to participate in tumor growth and metastasis in cervical cancer." (PMID 24797725, 2014). "In addition, Orai1 silencing and the pharmacological inhibition of Orai1-mediated SOCE attenuated the growth of cervical cancer cells." (PMID 36310590, 2022). "The levels of Orai1, STIM1, and HDAC6 were upregulated in cervical cancer cells." (PMID 36230965, 2022). "STIM1 and Orai1 are overexpressed in tumor tissues when compared with non-cancerous or precancerous tissues in patients with cervical cancers." (PMID 35008759, 2021). "In addition, a possible role of Orai1-mediated SOCE in cervical cancer has not been reported so far." (PMID 36310590, 2022). "Therefore, we next analyzed whether Orai1-regulated SOCE plays a key role in the expression and secretion of IL-6 in cervical cancer." (PMID 36310590, 2022). "Moreover, Orai1 has been demonstrated to be upregulated in cervical cancer, but not in related normal cells." (PMID 33333945, 2020).
cervical cancer (continued). "Interestingly, the expression of STIM1 and Orai1 was increased in most cervical cancer specimens, while the acetylation of tubulin was decreased, suggesting that specific targeting of HDAC6 in cervical cancer can inhibit STIM1-Orai1-mediated cervical neogenesis." (PMID 36230965, 2022). "To validate these results, we analyzed Orai1 mRNA levels in a cohort of 21 paired cervical cancer and normal tissues through RT-qPCR, and found that Orai1 expression was approximately five-fold higher in 62% (13/21) of the cervical cancer tissues compared to the matched normal tissues." (PMID 36310590, 2022).
lung carcinoma (10 papers, 2016 to 2021). "This notion of optimal levels of Ca2+ flux being important was supported by a study in which overexpression of Orai1 in A459 lung cancer cells inhibited EGF-mediated cell proliferation." (PMID 29568366, 2018). "The compound named “B” decreases the expression of both Orai1 and Orai3 in NCl-H460 lung cancer cell line, and tumour growth in vivo." (PMID 27835593, 2016). "The role of Ca2+ signaling through the SOCE pathway involving STIM1 and ORAI1 has been reported previously to affect the prognosis of cervical, colorectal, breast, esophageal, multiple myeloma, and lung cancers by affecting tumor growth, proliferation, metastasis, and survival." (PMID 32046188, 2020). "We hypothesised that TRPM7 and Orai1 may be involved in the regulation of lung cancer metastasis." (PMID 32684624, 2020). "In breast and lung cancer cells, soluble αKlotho has been reported to attenuate SOCE by inhibiting PI3K-driven cell surface expression of Orai1, leading to the suppression of SOCE-mediated tumor cell migration." (PMID 33916304, 2021). "Orai1 was a primary molecular component of SOCE in both breast and lung cancer cells, MDA-MB231 and H1693, respectively." (PMID 33386992, 2021). "In lung cancer, SOCE components including STIM1, ORAI1, and TRPC channels have been examined in a dataset of more than 2000 cases." (PMID 32046188, 2020). "On the contrary, overexpression of Ca2+ release-activated Ca2+ channel protein 1 (Orai1), also known as CRACM1, triggered reduction of store-operated Ca2+ influx and attenuation of EGF-mediated proliferative signaling and driving cell cycle arrest in A549 lung cancer cells." (PMID 36046435, 2021). "Therefore, we explored whether αKlotho inhibits Orai1-mediated SOCE and migration in breast and lung cancer cells." (PMID 33386992, 2021).
anhidrosis (9 papers, 2020 to 2025). Lack of sweating or the ability to sweat when provoked by the appropriate stimulus. "This is highlighted by the defects observed in patients with mutations in either STIM1 or Orai1—which phenocopy each other—including severe combined immunodeficiency, muscle hypotonia, ectodermal dysplasia, and anhidrosis with dry skin and heat intolerance." (PMID 39499286, 2025). "The finding that patients with LoF mutations in Orai1 present with anhidrosis suggests that an intimate association between Orai1 and TMEM16A exists, because other sources of Ca2+ cannot substitute for Orai1." (PMID 40459545, 2025). "Sweating depends on SOCE as patients with reduced SOCE due to mutations in either STIM1 or Orai1 suffer from anhidrosis." (PMID 39499286, 2025). "Patients with LoF mutations in STIM1 or Orai1 exhibit marked anhidrosis." (PMID 40459545, 2025). "Here we report the identification of a patient with a novel autosomal recessive mutation in ORAI1 associated with typical CRAC channelopathies, including CID, muscular hypotonia, and anhidrosis." (PMID 33650027, 2021). "Here we describe a novel mutation in ORAI1 that abolishes SOCE and causes CID associated with recurring viral and bacterial infections, neutropenia, muscular hypotonia, and anhidrosis in an infant." (PMID 33650027, 2021). "Mice lacking ORAI1 manifest reduced enamel mineralization and thinner skin with elongated keratinocytes and smaller vibrissae follicles, and the ectodermal-specific knockout of Orai1 or Stim1/Stim2 impairs SOCE and results in anhidrosis and a reduced sweat gland lumen." (PMID 33250786, 2020).
pancreatitis (9 papers, 2015 to 2025). Inflammation of the pancreas. "This underscores the potential for ORAI1 inhibitors to address both pancreatic and systemic inflammation, such as pancreatitis-associated acute lung injury." (PMID 39776917, 2024). "Furthermore, neutrophil-specific inhibition of the ORAI1 calcium channel reduced pancreatitis-associated acute lung injury, suggesting that targeting multiple cell types, including immune cells, is crucial for effectively treating the systemic complications of pancreatitis." (PMID 39776917, 2024). "In pancreatitis, the pathological rise in acinar cell cytosolic Ca2+ levels mediated by ORAI1 leads to mitochondrial dysfunction and cell death, exacerbating inflammation and tissue injury." (PMID 39776917, 2024). "Targeted inhibition of ORAI1 has emerged as a promising therapeutic approach to mitigate the effects of pancreatitis." (PMID 39776917, 2024). "The calcium release–activated calcium modulator ORAI1 is the most abundant Ca2+ entry channel in pancreatic acinar cells; it sustains calcium overload in mice exposed to toxins that induce pancreatitis." (PMID 25917787, 2015). "Additionally, the strategy of inhibiting ORAI1 has been found to be significantly more effective when administered early after the onset of pancreatitis, underscoring the importance of timing in therapeutic intervention to maximize efficacy." (PMID 39776917, 2024). "The use of ORAI1 inhibitors, such as CM4620, GSK-7975A and CM_128, has been suggested as a therapeutic approach, effectively reducing cytosolic Ca2+ overload in pancreatic cells and mitigating the inflammatory response associated with pancreatitis." (PMID 39776917, 2024). "This complex interaction between cholesterol and ORAI1 suggests that lipid regulation may also play a role in modulating the severity of inflammatory responses in conditions like pancreatitis." (PMID 39776917, 2024). "ORAI1 inhibitors might be developed for the treatment of patients with pancreatitis." (PMID 25917787, 2015). "ORAI1, an essential component of the SOCE pathway, plays a crucial role in calcium influx, which is critical for cellular functions and the inflammatory response during pancreatitis." (PMID 39776917, 2024).
pulmonary hypertension (9 papers, 2017 to 2025). Increased pressure within the pulmonary circulation due to lung or heart disorder. "Our findings demonstrated that Orai1 inhibition represents a novel and complementary therapeutic strategy for pulmonary arterial hypertension by acting at pulmonary vascular and RV levels." (PMID 41212057, 2025). "Considering that 2-APB is not a selective STOC blocker, new drugs with a selective effects on ORAI1/STIM1 interaction are needed to evaluate the role of the STOC in OSA patients with pulmonary hypertension." (PMID 35370769, 2022). "These new findings demonstrated that the Orai1-dependent Ca2+ current participated in cardiac Ca2+ remodeling in the right ventricular hypertrophy secondary to pulmonary hypertension." (PMID 33117812, 2020). "In right ventricular hypertrophy and dysfunction secondary to pulmonary hypertension, we also observed an increased Orai1 expression." (PMID 33117812, 2020). "We have demonstrated that Orai1 function contributes to human pulmonary arterial hypertension (PAH) and to several preclinical models of pulmonary hypertension (PH)." (PMID 36291148, 2022). "For example, Orai1-mediated SOCE is involved in the formation and development of pulmonary hypertension." (PMID 38540713, 2024). "Orai1, Orai12, and Orai3 can promote SOCE in PASMCs and may serve as potential therapeutic targets for chronic hypoxia-induced pulmonary hypertension." (PMID 30320134, 2018). "Together, these results suggested that the components of SOCCs, including Orai1, 2, 3 and STIM1, may lead to novel therapeutic targets for the treatment of chronic hypoxia-induced pulmonary hypertension." (PMID 29188077, 2017). "Both ORAI1 and ORAI2 are upregulated in pulmonary arterial smooth muscle cells (PASMCs) under hypoxic conditions and so could prove therapeutic targets for hypoxia-induced pulmonary hypertension." (PMID 38261554, 2024).